SIPA1L3 (signal induced proliferation associated 1 like 3)
Description:
Plays a critical role in epithelial cell morphogenesis, polarity, adhesion and cytoskeletal organization in the lens.
Synonyms: KIAA0545; SPAL3; SPAR3; CTRCT45
Tractability: Antibody: UniProt places it where antibodies can reach, with high confidence; its Gene Ontology location is reachable by antibodies, with high confidence; the Human Protein Atlas places it where antibodies can reach. PROTAC: ubiquitination databases record sites on it; its protein half-life has been measured.
Gene: Protein-coding gene on chromosome 19 (37,907,208 to 38,208,369, forward strand). Ensembl gene ENSG00000105738.
Subcellular location: Apical cell membrane
Subcellular location (Human Protein Atlas): Plasma membrane; Golgi apparatus; Nucleoplasm
Gene Ontology:
Molecular function: protein binding; GTPase activator activity
Biological process: epithelial cell morphogenesis; establishment of epithelial cell polarity; cytoskeleton organization; eye development; regulation of small GTPase mediated signal transduction
Cellular component: apical part of cell; apical plasma membrane; extracellular region; plasma membrane; stress fiber; tricellular tight junction; glutamatergic synapse; postsynaptic specialization, intracellular component
Genetic constraint (gnomAD): Loss-of-function variants: 59 observed, 131.16 expected, observed/expected ratio (o/e) 0.45, 90% interval 0.36 to 0.56. The upper end of that interval is the gene's LOEUF score, 0.56, which puts it in group 2 of 6, group 1 being the genes least tolerant of losing a copy. Missense variants: 2,195 observed, 2,422.7 expected, observed/expected ratio (o/e) 0.91, 90% interval 0.87 to 0.94. Synonymous variants: 1,063 observed, 1,051.8 expected, observed/expected ratio (o/e) 1.01, 90% interval 0.96 to 1.06.
Homologues: Orthologues: chimpanzee SIPA1L3 (99% identical), macaque SIPA1L3 (98% identical), rabbit SIPA1L3 (94% identical), guinea pig SIPA1L3 (92% identical), mouse Sipa1l3 (91% identical), rat Sipa1l3 (91% identical), pig SIPA1L3 (91% identical), dog SIPA1L3 (89% identical), tropical clawed frog sipa1l3 (63% identical), zebrafish sipa1l3 (56% identical), Drosophila melanogaster RapGAP1 (12% identical), Caenorhabditis elegans F53A10.2 (10% identical). Paralogues in human: SIPA1L1 (46% identical), SIPA1L2 (45% identical), SIPA1 (24% identical), GARNL3 (14% identical), RAP1GAP2 (13% identical), RAP1GAP (13% identical).
Diseases named in the same sentence as SIPA1L3 in open-access papers:
SIPA1L3 is named in the same sentence as 11 diseases in open-access papers, as found by Europe PMC text mining. Sharing a sentence is not in itself a finding about the gene and the disease. The quoted sentences say what the papers report.
cataract (1 paper, 2021). Partial or complete opacity of the crystalline lens of one or both eyes that decreases visual acuity and eventually results in blindness. "Collectively, our finding expands the mutation spectrum of SIPA1L3 and provides new clues to the molecular mechanisms of SIPA1L3-related cataracts." (PMID 34603379, 2021). "By using whole-exome sequencing plus Sanger sequencing validation, we identified a novel heterozygous c.1871A > G (p.Lys624Arg) variation within the predicted RapGAP domain of SIPA1L3 in the proband with isolated juvenile-onset cataracts from a three-generation Chinese family." (PMID 34603379, 2021).
diabetes (1 paper, 2016). "The previously identified UMOD locus showed genome-wide significant association with eGFRcrea among those with diabetes (rs12917707, P value=2.5 × 10−8), and six loci (NFKB1, UNCX, TSPAN9, AP5B1, SIPA1L3 and PTPRO) had nominally significant associations with eGFRcrea among those with diabetes." (PMID 26831199, 2016).
IgA nephropathy (1 paper, 2023). "In IgA nephropathy, LYZL1 and SIPA1L3 risk genotypes are related to the decrease of Dialister and Bacilli and the risk genotypes of PLTP and AL365503.1 were associated with increased abundance of Erysipelotrichaceae and Lachnobacterium." (PMID 38189041, 2023).
cancer (3 papers, 2015 to 2025). A tumor composed of atypical neoplastic, often pleomorphic cells that invade other tissues. "SIPA1L3 affects the proliferation and invasion of cancer cells both in vivo and in vitro." (PMID 41088697, 2025). "Very limited data are currently available regarding the role of SIPA1L3 in human carcinoma." (PMID 41088697, 2025).
tumor (3 papers, 2019 to 2025). "Given the absence of a second TSC2 variant, TSC2-LOH or any other evident tumor driver apart from the unclear variant in SIPA1L3 in the renal and hepatic AMLs of the herewith reported individual, a contribution of the germline ARID1B variant to the tumorigenesis cannot be excluded." (PMID 31077186, 2019).
SIPA1L3 also shares sentences with these, for which no sentence is quoted: asthma (1 paper); colorectal adenocarcinoma (1); glioblastoma (1); Juvenile onset (1); lung adenocarcinoma (1); lung carcinoma (1).